KLF7 (KLF transcription factor 7)
Description:
Transcriptional factor. Plays a critical role in neuronal morphogenesis and survival of sensory neurons (By similarity). Represses the corneal epithelium differentiation. Also acts as a metabolic regulator, by modulating insulin sensitivity in pancreatic beta cells and skeletal muscle cells. Inhibits transcriptional inducers of adipogenesis and has a repressive role in the expression of several adipokines, including leptin.
Synonyms: UKLF
Tractability: PROTAC: ubiquitination databases record sites on it.
Gene: Protein-coding gene on chromosome 2 (207,074,137 to 207,173,856, reverse strand). Ensembl gene ENSG00000118263.
Subcellular location: Nucleus
Subcellular location (Human Protein Atlas): Nucleoplasm; Cytosol
Gene Ontology:
Molecular function: DNA-binding transcription activator activity, RNA polymerase II-specific; DNA-binding transcription factor activity, RNA polymerase II-specific; RNA polymerase II cis-regulatory region sequence-specific DNA binding; zinc ion binding; DNA binding; DNA-binding transcription factor activity; sequence-specific double-stranded DNA binding
Biological process: glucose homeostasis; negative regulation of adipose tissue development; negative regulation of insulin secretion involved in cellular response to glucose stimulus; negative regulation of transcription by RNA polymerase II; positive regulation of transcription by RNA polymerase II; regulation of epidermal cell differentiation; axon guidance; axonogenesis; dendrite morphogenesis; regulation of transcription by RNA polymerase II; positive regulation of DNA-templated transcription
Cellular component: nucleoplasm; nucleus; chromatin
Genetic constraint (gnomAD): Loss-of-function variants: 2 observed, 28.72 expected, observed/expected ratio (o/e) 0.0696, 90% interval 0.027 to 0.22. The upper end of that interval is the gene's LOEUF score, 0.22, which puts it in group 1 of 6, group 1 being the genes least tolerant of losing a copy. Missense variants: 221 observed, 409.78 expected, observed/expected ratio (o/e) 0.54, 90% interval 0.48 to 0.6. Synonymous variants: 165 observed, 169.45 expected, observed/expected ratio (o/e) 0.97, 90% interval 0.86 to 1.11.
Homologues: Orthologues: chimpanzee KLF7 (100% identical), macaque KLF7 (99% identical), rabbit KLF7 (98% identical), dog KLF7 (98% identical), mouse Klf7 (97% identical), rat Klf7 (97% identical), guinea pig KLF7 (84% identical), pig KLF7 (82% identical), tropical clawed frog klf7 (77% identical), zebrafish klf7b (68% identical), zebrafish klf7a (67% identical), Drosophila melanogaster luna (49% identical). Paralogues in human: KLF6 (52% identical), KLF5 (37% identical), KLF12 (32% identical), KLF4 (32% identical), KLF2 (31% identical), KLF8 (30% identical), KLF3 (29% identical), KLF1 (29% identical), KLF11 (26% identical), KLF15 (26% identical), KLF10 (25% identical), SP5 (24% identical), and 10 more.
Diseases named in the same sentence as KLF7 in open-access papers:
KLF7 is named in the same sentence as 92 diseases in open-access papers, as found by Europe PMC text mining. Sharing a sentence is not in itself a finding about the gene and the disease. The quoted sentences say what the papers report.
Obesity (14 papers, 2015 to 2024). Accumulation of substantial excess body fat. "A growing body of evidence has suggested that KLF7 is associated with human obesity, type II diabetes and cardiovascular diseases, and KLF7 is one of five specific core transcription factors that regulate coronary artery disease associated pathways." (PMID 36810848, 2023). "This identified four enriched motifs, including KLF7, which has previously been implicated in adipogenesis, obesity and glucose-related pathological mechanisms, and inflammatory signaling pathways in adipose tissue." (PMID 37452040, 2023). "Collectively, these results suggested that obesity facilitates KLF7/CCL2 expression of BMA in the bone marrow cavity." (PMID 38221626, 2024). "In summary, this study confirmed elevated levels of FFA C8:0 in obesity can up-regulate the transcription factor KLF7 through fatty acid receptor GPR84." (PMID 37170248, 2023). "In this study, we determined the expression levels of GPR84, KLF7, IL-6, p21 in tumor tissues of patients with PCa and obesity with primary PCa tumor-bearing mouse model." (PMID 37170248, 2023). "Our previous results have shown that obesity-induced excessive palmitic acid (PA) can promote the expression of KLF7, which plays a vital role in regulation of inflammation, glucose metabolism." (PMID 35443706, 2022). "Our results indicate that obesity-induced elevated palmitic acid promotes inflammation and glucose metabolism disorders through GPRs/NF-κB/KLF7 signaling pathway." (PMID 35443706, 2022). "In summary, this study shows that increasing PA content after obesity induces inflammation and glucose metabolism disorders through GPRs/NF-κB/KLF7 signaling pathways." (PMID 35443706, 2022). "Blocking GPRs/NF-κB in diet-induced obesity mice to detect the expression of KLF7, inflammatory cytokines and glucose metabolism related factors, clarifying the effects of GPRs/NF-κB on KLF7 in vivo." (PMID 35443706, 2022). "Previous reports on mammalian species showed that KLF7 regulated neuroectodermal and mesodermal development and played a role in obesity, T2DM, and blood disease." (PMID 33054719, 2020). "Whereas, genetic correlation analysis indicated that KLF7 is a candidate gene for human obesity, which inhibits the differentiation of adipose precursor cells and downregulates many genes involved in adipose differentiation." (PMID 32933085, 2020). "KLF7 had been reported as a key regulator of human obesity, diabetes mellitus type 2 (T2DM), and blood disease." (PMID 33054719, 2020). "In summary, high concentrations of free fatty acids play an important role in the activation of TLR4/NF-κB/IL-6 inflammatory signaling pathways by promoting the expression of KLF7 in obesity." (PMID 30598636, 2018). "Exploring the specific molecular mechanism of KLF7 involvement in this process would provide a new target for the treatment of obesity, inflammation, and related metabolic diseases." (PMID 30598636, 2018). "Investigation of KLF7 gene polymorphismsrevealed an association with T2DM risk in the Japanese population and aprotective effect against obesity in the Danish population." (PMID 26483964, 2015). "KLF7 is reportedly related to neurogenesis, progression of type 2 diabetes, obesity, and regulation of thymocyte development." (PMID 25985088, 2015). "The synteny between KLF6 and KLF7 may collectively regulate intramuscular fat deposition and obesity in the organism." (PMID 39272379, 2024). "Moreover, HFD-induced obesity promoted KLF7/CCL2 expression in BMA and PCa cell growth in the bone marrow cavity of the mice." (PMID 38221626, 2024). "After clarifying that the transcription factor KLF7 plays an important role in the development of obesity-induced PCa, searching for key downstream target genes of KLF7 may provide important experimental evidence for the treatment and prevention of PCa." (PMID 37170248, 2023).
Obesity (continued). "The negative correlation of KLF7 expression to the fasting glycaemia in chicken and abdominal fat content, suggested that a feedback regulation among KLF7 expression, glycaemia, and obesity might exist in chicken." (PMID 33054719, 2020). "Above all, previous studies have shown that KLF7 may closely relate to IL-6 overexpression induced by high levels of free fatty acids in obesity." (PMID 30598636, 2018). "There are few researches on KLF7 in the obesity-induced inflammation." (PMID 30598636, 2018). "In human adipocytes, KLF7 expression is involved in adipogenesis, obesity and type 2 diabetes." (PMID 28525384, 2017). "Best studied are hitherto microRNAs during adipogenesis and obesity, where miR-146b regulates the proliferation of visceral pre-adipocytes and promote their differentiation, a target of Krüppel-like transcription factor KLF7." (PMID 27147943, 2016). "Notably, associations with obesity-related SNPs have been reported separately for KLF6 and KLF7." (PMID 39272379, 2024). "The present study aimed to determine whether obesity-induced elevation in palmitic acid (PA), which is the most abundant of the free fatty acids (FFAs), increased CCL2 via the GPRs/KLF7 pathway in bone marrow adipocytes (BMA) to facilitate PCa growth and metastasis." (PMID 38221626, 2024). "More importantly, our laboratory also found that obesity-induced high concentration of PA could significantly promote KLF7 expression, while the specific mechanism was not elucidated fully." (PMID 35443706, 2022).
gastric cancer (11 papers, 2020 to 2024). A primary or metastatic malignant neoplasm involving the stomach. "For example, KLF7 overexpression has been associated with increased cell proliferation in gastric cancer cells, implying an oncogenic role in promoting tumor growth." (PMID 38116138, 2023). "For instance, KLF7 has been implicated as a tumor promoter in oral squamous carcinoma, pancreatic cancer, hepatocellular carcinoma or gastric cancer, but its role in colorectal cancer has been elusive." (PMID 36890812, 2023). "The DNA methylation in KLF7 is reported to be associated with the occurrence and development of gastric cancer in humans." (PMID 33054719, 2020). "KLF7 was also reported to exhibit a significantly positive correlation with malignancy development in glioma, gastric cancer, and oral squamous cell carcinoma." (PMID 38221626, 2024). "KLF7 is also overexpressed in gastric cancer samples and it encourages the migration and invasion of gastric cancer cells." (PMID 33892667, 2021). "Since it served as a risky indicator in clinic consequences of malignancies like ovarian cancer, squamous carcinomas and gastric cancer 43-45, it is quite plausible to suggest that that KLF7 acted as a wicked downstream gene of the ceRNA crosstalk in PC." (PMID 34659523, 2021). "Previous studies suggested that dysregulation of KLF7 played crucial roles in several solid tumors, including non-small-cell lung cancer and gastric cancer." (PMID 33858520, 2021). "Studies have shown that KLF7 is up‐regulated in gastric cancer." (PMID 35028969, 2022). "Overexpression of KLF7 promotes the proliferation and migration of gastric cancer cells." (PMID 35028969, 2022). "The previous studies in humans showed that DNA methylation of KLF7 was associated with the occurrence and development of gastric cancer, however, there is no report on the DNA methylation of KLF7 in adipose tissue and birds." (PMID 33054719, 2020). "In addition, KLF7 was an oncogene in several kinds of cancers, including gastric cancer, lung adenocarcinoma, glioma and oral squamous cell carcinoma." (PMID 33054719, 2020). "This study aimed to investigate the clinical characteristics of miR-450b-3p in the patients of gastric cancer (GC), and further explore whether miR-450b-3p could inhibit the proliferation of GC cells via regulating KLF7." (PMID 32063748, 2020). "Krüppel-like factor 7 (KLF7) is a member of the KLF family of zinc finger transcription factors and has antioncogenic functions in multiple cancer, such as human oral squamous cell carcinoma (OSCC), glioma, gastric cancer, endometrial cancer, ovarian cancer, and non−small cell lung cancer." (PMID 35757722, 2022).
glioma (11 papers, 2019 to 2025). A benign or malignant brain and spinal cord tumor that arises from glial cells (astrocytes, oligodendrocytes, ependymal cells). "Additionally, Krüppel-like factor 7 (KLF7) is known to be over-expressed in glioma, and further negatively-associated with patients' overall survival (OS) by augmenting cancer cellular progression and tumor formation." (PMID 34659523, 2021). "As has been reported for Akt and Ras signaling in gliomas, KLF7 upregulates translation independently of increased transcription rate." (PMID 36192788, 2022). "Integration of this bioinformatic analysis with the previous studies, we observed that KLF7 was a direct target of miR-136-3p in gliomas." (PMID 32677950, 2020). "Base on comprehensive consideration of both the bioinformatic prediction and the previous studies, we can conclude that KLF7 is an oncogene in glioma or other cancers." (PMID 32677950, 2020). "The data showed that overexpression of KLF7 can partly block overexpression of miR-136-3p-mediated suppression of glioma progression by regulating cell growth, migration, and apoptosis of cancer cells." (PMID 32677950, 2020). "In this study, we observed that KLF7 expression was inhibited by overexpression of miR-136-3p, and KLF7 levels was increased by knockdown of miR-136-3p in cancer cells, indicating that KLF7 was a direct target of miR-136-3p in glioma." (PMID 32677950, 2020). "Herein, we investigated the role of miR-136-3p/KLF7 axis in glioma cell proliferation, migration, and apoptosis, and we also explored the potential molecular mechanisms." (PMID 32677950, 2020). "Firstly, we found that overexpression of KLF7 partly blocked miR-136-3p-regulated glioma cell growth, migration, and apoptosis of LN-229 and U251 cells." (PMID 32677950, 2020). "Tumor-bearing experiment in nude mice was performed to comprehensively investigate the role of miR-136-3p/KLF7 axis in gliomas." (PMID 32677950, 2020). "On the other hand, hsa-miR-136-3p promotes the tumorigenesis of glioma by binding to KLF7." (PMID 39684278, 2024). "For example, miR-136-3p inhibits the occurrence of gliomas by targeting KLF7 in vivo." (PMID 37834341, 2023). "KLF7 is an oncogene that is adversely controlled by miR-136-3p in glioma and other malignancies." (PMID 35626359, 2022). "Then, in vitro and in vivo experiments were performed to determine whether KLF7 was required for miR-136-3p exerting its functions in glioma." (PMID 32677950, 2020). "The results also encourage that miR-136-3p and KLF7 might be promising novel biomarkers and therapeutic targets for glioma patients’ treatment." (PMID 32677950, 2020). "Herein, we investigated the role of miR-136-3p and its target gene KLF7 in glioma development." (PMID 32677950, 2020). "Importantly, KLF7 can enhance glioma progression by transcriptionally activating argininosuccinate lyase." (PMID 32677950, 2020). "To determine whether KLF7 is necessarily required for function of miR-136-3p in glioma development, we co-overexpressed KLF7 and miR-136-3p in LN-229 and U251." (PMID 32677950, 2020). "Furthermore, we observed that KLF7 was a direct target of miR-136-3p, and KLF7 was negatively regulated by miR-136-3p in glioma cells." (PMID 32677950, 2020). "Moreover, a previous study reported that KLF7 transcriptionally activated argininosuccinate lyase, which resulted in polyamines production and the oncogenesis of glioma." (PMID 31552163, 2019). "Targeting miR-136-3p/KLF7 axis might be a novel manner to counter against gliomas." (PMID 32677950, 2020). "Previous studies have revealed that KLF7 can promote polyamine biosynthesis and glioma development by activating argininosuccinate lyase, and meanwhile, KLF7 can be modulated by Linc00669/miR-193a axis and it can advance non-small cell lung cancer, suggesting that KLF7 is an oncogene." (PMID 32677950, 2020). "Consequently, we can conclude that KLF7 is an oncogene in cancers, such as glioma." (PMID 32677950, 2020).
glioma (continued). "Known gene targets for miR-136-3p include Kruppel-like factor 7 (KLF7), whose downregulation suppresses glial tumor formation, and Phosphatase and TENsin homolog (PTEN), which regulates bone and blood vessel formation." (PMID 41465589, 2025).
hepatocellular carcinoma (10 papers, 2021 to 2025). A malignant tumor that arises from hepatocytes. "Similar associations between KLF7 expression and clinicopathological features have been reported in other types of cancer, such as hepatocellular carcinoma, where high KLF7 expression has been linked to larger tumor size, lymph node metastasis, and advanced clinical stage." (PMID 38116138, 2023). "In hepatocellular carcinoma, it sponges miR‐186‐5p, thereby derepressing KLF7 and activating the Wnt/β catenin pathway." (PMID 40903777, 2025). "In line with this, another study demonstrated that the transcriptional activation of VPS35 by KLF7 propels hepatocellular carcinoma cells growth and metastasis by activating Ccdc85c-medicated β-catenin pathway." (PMID 40484931, 2025). "Recent studies have also shown that KLF7 was downregulated in hepatocellular carcinoma (HCC), circUBE2J2 acted as a competing endogenous RNA to control KLF7 expression by sponging miR-370-5p." (PMID 35443866, 2022). "In summary, KLF7/VPS35 axis contributes to hepatocellular carcinoma progression through CCDC85C-mediated β-catenin pathway." (PMID 33858520, 2021). "Similarly, in hepatocellular carcinoma, it binds miR-186-5p to derepress KLF7 and activate the Wnt/β catenin pathway, enhancing proliferation and EMT." (PMID 40903777, 2025). "The aim of this study was to investigate the role of KLF7 in proliferation and migration of hepatocellular carcinoma (HCC) cells." (PMID 33858520, 2021).
pancreatic cancer (9 papers, 2021 to 2023). "KLF7 knockdown in vitro and in vivo reduces pancreatic cancer cell proliferation and tumor growth, respectively." (PMID 37239940, 2023). "A miR-185-5p/KLF7 axis exists in pancreatic cancer such that downregulated miR-185 results in decreased tumor suppression, and increased KLF7 drives oncogenic cytokine production, proliferation, and migration." (PMID 36077352, 2022). "KLF7 promotes pancreatic cancer growth and metastasis by upregulating ISGs that include IFI6, interferon-induced protein with tetratricopeptide repeats 1 (IFIT1) and IFIT328." (PMID 34650128, 2021). "A role of KLF7 in Golgi apparatus has been recently demonstrated in pancreatic cancer]." (PMID 36192788, 2022). "The Krüppel-like factor 7 (KLF7), a member of the Krüppel-like factor family, has garnered attention for its involvement in various cancers, such as breast, lung, and pancreatic cancers." (PMID 38116138, 2023). "The current study set out to investigate the role of long intergenic non-protein coding RNA (LINC) 00152 in pancreatic cancer (PC) cell glycolysis with the microRNA (miR)-185-5p/Krüppel-like factor 7 (KLF7) axis." (PMID 34659523, 2021).